CD14 (CD14 molecule)
Diseases named in the same sentence as CD14 in open-access papers (continued):
Sharing a sentence is not in itself a finding about the gene and the disease.
esophageal SCC (2 papers, 2014 to 2017). "Our clinical data suggested that the level of CD11b+CD14+HLA-DR− myeloid cells was linked to the progression of esophageal SCC." (PMID 25238263, 2014). "We examined the percentage of CD11b+CD14+HLA-DR− myeloid cells and the levels of IL-6 in the peripheral blood of 50 patients with esophageal SCC and 12 healthy controls." (PMID 25238263, 2014). "FACS analysis revealed that the number of CD11b+CD14+HLA-DR- cells significantly increased in the PB of the esophageal SCC patients compared with the healthy donors." (PMID 25238263, 2014). "Here we demonstrated that circulating CD11b+CD14+HLA-DR− cells were significantly increased in esophageal SCC patients compared with healthy people, and this was associated with the clinical stage, treatment response and circulating IL-6 levels." (PMID 25238263, 2014). "To evaluate the clinical significance of the CD11b+CD14+HLA-DR− subset in the esophageal SCC patients, we further analyzed these cells according to clinical tumor parameters." (PMID 25238263, 2014). "The mean percentage of CD11b+CD14+HLA-DR− cells relative to the total number of CD11b+ myeloid cells in the PBMCs of esophageal SCC patients was 42.2±9.7% compared to 5.18±1.3% in healthy donors." (PMID 25238263, 2014). "The percentage of CD11b+CD14+HLA-DR− cells in the peripheral circulation of patients with esophageal SCC and healthy controls was evaluated using flow cytometry." (PMID 25238263, 2014). "In the present study, we characterized the percentage of CD11b+CD14+HLA-DR- myeloid cells in a cohort of esophageal SCC patients." (PMID 25238263, 2014). "Our results are consistent with a recent study of esophageal squamous cell carcinoma (SCC) where IL-6 induced the accumulation of CD11b+CD14+HLA-DR− MDSC by stimulating STAT3 signal and its level in plasma samples was correlated with tumor progression and poor prognosis." (PMID 29100353, 2017). "Therefore, we focused our work to assess the predictive value of CD11b+CD14+HLA-DR− myeloid cells in patients with esophageal SCC." (PMID 25238263, 2014).
gastroenteritis (2 papers, 2015 to 2017). An inflammatory disorder that affects the upper and lower gastrointestinal tract. "Inhibited expression of the LPS-binding receptor CD14 was shown to be associated with increased susceptibility to gastroenteritis and UC and the expression of GM-CSF receptor was shown to be higher in healthy individuals than in UC or CD patients." (PMID 25944986, 2015).
Gaucher disease (2 papers, 2011 to 2019). Gaucher disease (GD) is a lysosomal storage disorder encompassing three main forms (types 1, 2 and 3), a fetal form and a variant with cardiac involvement (Gaucher disease - ophthalmoplegia - cardiovascular calcification or Gaucher-like disease). "Patients with Gaucher's disease and patients with phenylketonuria have more CD14+CD16+ monocytes in peripheral blood than matched controls." (PMID 30941138, 2019). "Indeed, some Gaucher disease patients had increased levels of pro-inflammatory (i.e., TNFα, IL-6, IL-8, and IL-1β) and anti-inflammatory cytokines (i.e., CD14) in serum and/or tissues." (PMID 21223590, 2011). "An in situ study of spleen from a Gaucher disease patient showed increased expression of anti-inflammatory mediators in macrophages, including CCL18, CD163, chitotriosidase, IL-1Ra, and CD14." (PMID 21223590, 2011). "Here, it was shown that Gaucher's disease blood contained a higher percentage of non-classical/inflammatory CD14+CD16+ cells compared to the classical CD14+CD16– monocytes." (PMID 30941138, 2019).
gingivitis (2 papers, 2019 to 2025). A disorder involving inflammation of the gums; may affect surrounding and supporting structures of the teeth. "In particular, according to the reported studies, genetic polymorphisms of VDR TaqI (rs731236), CD14 −260C/T, IL10-592-C, IL-1Ra, and TLR4-299-G were associated with higher risk of developing gingivitis." (PMID 41300760, 2025). "Gingivitis and cariogenic biofilms had little effect on both pathways except for gingivitis biofilm increasing CD14 and both biofilms increasing IRAK2 significantly." (PMID 31448244, 2019). "Besides the upregulation induced by the commensal biofilm, we also found that gingivitis biofilm significantly up-regulated CD14; gingivitis and cariogenic biofilms both up-regulated IRAK2 transcription; while the cariogenic biofilm slightly suppressed CD14, IRAK4, and IRF3 transcription." (PMID 31448244, 2019). "In comparison, gingivitis biofilm activated fewer genes (e.g., TLR4) and cariogenic biofilm suppressed CD14, IRAK4, and IRF3 transcription." (PMID 31448244, 2019).
glaucoma (2 papers, 2019 to 2024). Increased pressure in the eyeball due to obstruction of the outflow of aqueous humor. "The authors observed an up-regulation of many proteins in AH from glaucoma patients, which were mostly related to innate immunity, for example higher values of CD14 and CD163, which are monocyte/macrophage markers." (PMID 30967499, 2019).
Graves disease (2 papers, 2011 to 2024). Graves' disease is an autoimmune disorder that leads to overactivity of the thyroid gland (hyperthyroidism).It is caused by an abnormal immune system response that causes the thyroid gland to produce too much thyroid hormones. "A noncoding RNA transcript Heg is negatively related to TRAb in untreated patients with Graves' disease and to CD14 mRNA in treated patients and controls." (PMID 22363873, 2011). "We have previously shown that a long non-coding RNA transcript Heg in MNC (GenBank EU137727) is negatively correlated with TRAb in patients with early and untreated Graves' disease and with CD14 mRNA in treated patients and in normal subjects." (PMID 22363873, 2011). "We have previously shown that a long noncoding RNA transcript Heg is negatively correlated with TSH receptor autoantibodies (TRAb) in patients with untreated Graves' disease and with CD14 mRNA in treated patients and controls." (PMID 22363873, 2011). "Patients with high Heg RNA concentrations had low TRAb values or CD14 mRNA values in untreated patients with Graves' disease and in treated patients and controls, respectively." (PMID 22363873, 2011). "Most notably, Actinobacteria (p) presented protective effects on Hashimoto’s thyroiditis via CCR2 on myeloid Dendritic Cell (5.0%), and Bifidobacterium (g) showed facilitating effects on Graves’ disease through CD39+ CD4+ T cell %CD4+ T cell (5.0%) and CD14 on CD33+ HLA DR+ CD14dim (12.2%)." (PMID 39351300, 2024).
H. pylori (2 papers, 2013 to 2014). "Notably, compelling evidence indicates that CD14 levels are closely associated with H. pylori disease outcome, suggesting that CD14 may be an important factor for determining the progression of H. pylori infection-associated gastric malignancy." (PMID 23338226, 2013).
hematoma (2 papers, 2023 to 2024). A hematoma is a collection of blood from a vascular structure into an extravascular space. "Pfkl is a subtype of Pfk, and in a previous transcriptomics study, the elevated level of Pfk gene expression in CD14+ monocytes/macrophages from hematoma tissue was reported to be significantly associated with good outcomes for ICH patients at the subacute stage." (PMID 38590360, 2024).
hip fracture (2 papers, 2023 to 2025). Traumatic or pathological injury to the hip in which the continuity of either the femoral head, femoral neck, intertrochanteric or subtrochanteric regions is broken. "In this study, we analyzed the composition and gene expression profiles of peripheral blood mononuclear cells (PBMCs) from elderly hip fracture patients by scRNA-seq and further identified new CD14 monocyte subpopulations based on marker genes and transcriptional profiles." (PMID 37848979, 2023).
HIV dementia (2 papers, 2017 to 2022). "More specifically, the CD14+ CD16+ monocyte subset was shown to enter the CNS, and cells expressing CD14 and CD16 in HIV encephalitis brain tissue were found to contain HIV protein." (PMID 29066542, 2017).
Hurler syndrome (2 papers, 2020 to 2021). Hurler syndrome is the most severe form of mucopolysaccharidosis type 1 (MPS1), a rare lysosomal storage disease, characterized by skeletal abnormalities, cognitive impairment, heart disease, respiratory problems, enlarged liver and spleen, characteristic facies and reduced life expectancy. "We present four cases of the severe form of MPS I or Hurler syndrome, demonstrating successful and stable CD14/15 donor chimerism following the prospective application of model-based dosing and TDM aimed to achieve lower busulfan exposure." (PMID 32781600, 2020).
hypoglycaemia (2 papers, 2017 to 2024). "Phenotypically, hypoglycaemia induced a shift from classical CD14+ monocytes towards more pro-inflammatory non-classical CD16+ monocytes in both groups (p < 0.001)." (PMID 38331900, 2024).
IgA Nephropathy (2 papers, 2018 to 2020). "Previous study showed that aberrant expansion of (CD14+CD16+) monocyte subsets contributed to the enhanced apoptotic phenotype in the pathogenesis of IgA nephropathy." (PMID 33551990, 2020).
Impaired glucose tolerance (2 papers, 2021 to 2024). An abnormal resistance to glucose, i.e., a reduction in the ability to maintain glucose levels in the blood stream within normal limits following oral or intravenous administration of glucose. "Other studies have reported that CD14-deficient mice have impaired glucose tolerance at older ages compared with wild-type." (PMID 38817635, 2024).
intracerebral hemorrhage (2 papers, 2020 to 2024). A cerebrovascular disorder characterized by bleeding into one or both cerebral hemispheres including the basal ganglia and the cerebral cortex. "The role of HAVCR2 in nerve injury was shown in patients with spontaneous intracerebral hemorrhage whose increased HAVCR2 expression on CD14+ monocytes was associated with systemic inflammatory response and sub-acute brain injury." (PMID 32140464, 2020). "They found that IL‐4, CD14, IL‐6R, and MSR1 were associated with intracerebral hemorrhage and lesion counts on MRI, while TLR4, CD14, IL‐6R, and IGH were linked solely with lesion counts." (PMID 39654683, 2024).
leukocytosis (2 papers, 2024 to 2026). "The observed increase in the CD14 protein serum concentrations 180 min after exercise could be interpreted as an indirect marker for leukocytosis." (PMID 38732600, 2024).
Listeria monocytogenes infection (2 papers, 2017). "Similar enrichment was observed using human CD14+ monocyte-derived macrophages with Listeria monocytogenes infection or mouse microglia with LPS challenge." (PMID 28737175, 2017).
lung squamous cell carcinoma (2 papers, 2022 to 2023). "Consistent with this, in the patient cohort with squamous cell lung cancer, the higher levels of CD14 TME expression were correlated with post-operative disease recurrence." (PMID 36139660, 2022).
Lyme borreliosis (2 papers, 2009 to 2019). "Macrophages express CD14 which partners with Toll-like receptor 2/1 to recognize bacterial lipoproteins such as those of Borrelia burgdorferi, the causative agent of Lyme disease." (PMID 20011115, 2009). "However, contrary to these paradigms, our prior study using a mouse model of Lyme disease demonstrated an association between CD14 deficiency, increased bacterial burden, and more severe and persistent disease." (PMID 20011115, 2009). "A similar increase in Lyme disease susceptibility characterized by increased tibiotarsal joint thickness, enhanced production of pro-inflammatory cytokines, and greater bacterial burden also was observed in CD14−/− C57BL/6 mice." (PMID 20011115, 2009). "More broadly, it also demonstrates that, notwithstanding similarities in the exaggerated Lyme disease phenotype observed in CD14−/− and TLR2−/− mice, these two signaling pathways are not entirely synonymous." (PMID 20011115, 2009). "The mouse model of Lyme disease was used to elucidate the relationship between CD14 signaling, SOCS activity, and disease progression." (PMID 20011115, 2009). "CD14 expression is not different between healthy donors and persistent Lyme borreliosis patients (p = 0.37)." (PMID 31366164, 2019).
macular edema (2 papers, 2021 to 2023). "Hence, it is likely that the proinflammatory CD14++ MC may promote angiogenesis and macular edema with up-regulated VEGFA-VEGFR2 pathway." (PMID 34594230, 2021).
malnutrition (2 papers, 2016 to 2017). Inadequate nutrition resulting from poor diet, malabsorption, or abnormal nutrient distribution. "In the PROVIDE study, selected predictors such as HAZ at week 18, MPO at week 12, and soluble CD14 at week 18 offer a potential explanation for the burden of malnutrition problems in low-income countries, allow early identification of infants at risk, and suggest pathways for intervention." (PMID 28293424, 2017).
mesothelioma (2 papers, 2023). A usually malignant and aggressive neoplasm of the mesothelium which is often associated with exposure to asbestos. "We report that the expression of ChemR23 coding gene, CMKLR1, in breast and mesothelioma tumors positively correlates to the expression of TAM markers such as CD14, CD163, MRC1 and HLA-DRA, in agreement with ChemR23 detection restricted to macrophages in tumors from patients." (PMID 37539056, 2023).
metastatic cancer (2 papers, 2012 to 2020). A carcinoma which has spread from the original site of growth to another anatomic site. "CD11b+CD14-MHCII- cells have been identified as MDSCs in the peripheral blood of dogs in both solitary and metastatic cancer and these cells were able to suppress T cell proliferation similar to what we found with CD11blowCADO48Alow cells." (PMID 23110794, 2012). "Using this method, blood is taken from subjects with metastatic cancer, processed by exclusion of CD45 + cells and capturing of EpCAM + cells in the VERSA, and stained for Hoechst, cytokeratin, and exclusion markers (CD11b, CD45, CD14, CD34)." (PMID 32255253, 2020).
Miscarriage (2 papers, 2017 to 2022). A pregnancy that ends at a stage in which the fetus is incapable of surviving on its own, defined as the spontaneous loss of a fetus before the 22th week of pregnancy. "In comparison with normal pregnancy, we observed a decrease in RANKL expression in trophoblasts and DSCs, as well as reduced RANK expression on CD14+dMφ in miscarriage, accompanied by a decreased frequency of dMφ with an M2 phenotype and an increase in the M1 phenotype." (PMID 29022922, 2017). "Consistently, the frequency of immunosuppressive monocytes, characterized by CD14+HLA-DR−/low, was increased in early pregnancy and reduced MDSC levels in blood and endometrium were found in miscarriage patients when compared to the normal pregnant control." (PMID 35180876, 2022).
monoclonal gammopathies (2 papers, 2018 to 2025). "For this purpose, CD14+ monocytes were purified from BM aspirates of patients with monoclonal gammopathies and cultured for 12–15 days in a medium containing the differentiating agents RANKL and M-CSF in the presence or absence of Glu." (PMID 40721650, 2025). "The preliminary results that we report here are in keeping with those of a recent study that also demonstrated increased activity of CD14/CD16+ monocytes in different monoclonal gammopathies in a hierarchical pattern." (PMID 29589834, 2018).
myeloid neoplasm (2 papers, 2022 to 2023). Proliferation of myeloid cells originating from a primitive stem cell. "The following surface antigens were selected for analysis: for myeloid tumors: MV-4-11, Thp-1, HL-60—CD11b, CD14, K562 and KG-1—CD34, and CD38; for lymphoid neoplasms: Raji, Daudi, U2932—CD19, CD20, Jurkat—CD4, CD8." (PMID 35053549, 2022). "In this tissue, CD38+ and CD14+ antibody staining is not strictly restricted to single lineages, and these markers can be aberrantly expressed in myeloid neoplasms included in this data set." (PMID 36959190, 2023).
Nasal polyps (2 papers, 2020). "Nasal polyps from three patients with chronic rhinosinusitis as well as control non-polyp nasal mucosa were used to isolate and cultivate mesenchymal stem cells characterized as CD73+, CD90+, CD105+/CD14−, CD34−, and CD45−." (PMID 33287173, 2020). "Elevated protein level of CD14 in noneosinophilic nasal polyps might be indicative of high LPS exposure in NECRSwNP." (PMID 32039442, 2020).
neuropathy (2 papers, 2017 to 2020). A disorder affecting the nervous system that manifests with pain, tingling, numbness, and/or muscle weakness. "Additionally, circulating levels of CD45_bright/CD14+/OCN+ were neither associated with proliferative diabetic retinopathy (p = 0.31) nor neuropathy (p = 0.53)." (PMID 28915881, 2017). "A study in HIV-infected patients with peripheral neuropathy found an increase in blood and CSF NEO levels, compared to HIV patients without neuropathy, together with an increase in CD14 + CD16 + monocytes." (PMID 32973438, 2020).
oligoarticular JIA (2 papers, 2020 to 2021). "In this study of children with oligoarticular JIA, we observed an increased frequency of synovial CD14+CD16+ monocytes." (PMID 32787920, 2020). "These authors discovered that while classical CD14++CD16− Mos dominate in the circulation, intermediate CD14++CD16+ Mos were highly enriched in oligoarticular JIA and ERA patient SF." (PMID 34360720, 2021).
oral squamous cell carcinoma (2 papers, 2022 to 2025). "While prior studies have implicated extracellular ENO1 in CD14-dependent TLR4 signaling in monocytes and a paracrine ENO1/TLR4/IL-6 axis driving metastasis in oral squamous cell carcinoma, its direct interaction with TLR4 in GBM remained unexplored." (PMID 41353343, 2025). "Moreover, in oral squamous cell carcinoma, PAI-1 has been shown to induce CD14+ monocytes to differentiate into CD206+ tumor-associated macrophages (TAMs), producing epidermal growth factors to mediate tumor cell migration." (PMID 35425712, 2022).
paroxysmal nocturnal hemoglobinuria (2 papers, 2010 to 2026). Paroxysmal nocturnal hemoglobinuria (PNH) is an acquired clonal hematopoietic stem cell disorder characterized by corpuscular hemolytic anemia, bone marrow failure and frequent thrombotic events. "However, patients with paroxysmal nocturnal hemoglobinuria have normal sCD14 levels in their sera, although monocytes from these patients do not express CD14 on their surface." (PMID 21172039, 2010).
plaque psoriasis (2 papers, 2020 to 2023). "We found that the frequency of Mo-MDSCs (CD14+HLA-DR−/low cells) among CD14+ cells from plaque psoriasis patients with blood-stasis (BS) syndrome was significantly increased when compared with healthy controls (p < 0.001) and blood-heat (BH) syndrome group (p < 0.001), respectively." (PMID 32382290, 2020). "Its receptor, DR3, is also reported to be expressed by PBMCs in psoriasis vulgaris, especially by CD8+ and CD14+ PBMCs." (PMID 36768135, 2023).
Plasmodium vivax malaria (2 papers, 2010 to 2014). Malaria resulting from infection by Plasmodium vivax. "The phenotype of plasma circulating MPs during acute vivax malaria was investigated, with specific mAbs for cell markers i.e. CD41a, CD235a, CD45, CD144 and CD14 were used to discriminate the cellular sources of annexin V+ MPs." (PMID 21080932, 2010).
pneumococcal infection (2 papers, 2007 to 2012). Infections with bacteria of the species streptococcus pneumoniae. "As we have previously reported during pneumococcal infection, CD14+ monocytes were highly susceptible to cell death." (PMID 22829769, 2012). "Interestingly TLR2/CD14 KO mice produced less TNF than wt mice, which indicates that besides TLR2 as the major regulator, CD14 participates in a temporally and locally coordinated action in controlling TNF during pneumococcal infection." (PMID 17428319, 2007).